TXN (thioredoxin)
Diseases named in the same sentence as TXN in open-access papers (continued):
Sharing a sentence is not in itself a finding about the gene and the disease.
Cirrhosis (1 paper, 2015). A chronic disorder of the liver in which liver tissue becomes scarred and is partially replaced by regenerative nodules and fibrotic tissue resulting in loss of liver function. "High serum concentrations of thioredoxin differentiated HCC from chronic liver diseases and cirrhosis (0.901 [0.875–0.923] in the training cohort; 0.906 [0.870–0.925] in the validation cohort)." (PMID 25871387, 2015). "The median levels of serum thioredoxin was 45.1 (IQR, 28.2–56.0) ng/ml, which was significantly higher than that of healthy subjects, patients with cirrhosis and chronic liver diseases (P < 0.0001)." (PMID 25871387, 2015).
corneal infection (1 paper, 2019). A viral or bacterial infectious process affecting the cornea. "A previous study has suggested targeting antioxidant pathways by pharmacological inhibition of thioredoxin in fungal pathogens as a successful therapy for experimental corneal infection in mice." (PMID 31481939, 2019). "Previous work has shown that targeting antioxidant pathways in fungal pathogens by pharmacological thioredoxin inhibition could prevent corneal infection." (PMID 31481939, 2019).
Crohn disease (1 paper, 2020). A gastrointestinal disorder characterized by chronic inflammation involving all layers of the intestinal wall, noncaseating granulomas affecting the intestinal wall and regional lymph nodes, and transmural fibrosis. "Among the 81 queried DEGs related to Crohn’s disease, 7 genes (IL-7, GATA3, CD28, CD5, TXN, ETS-1, and CCR7) were introduced as dysregulated genes." (PMID 33585004, 2020). "Through network analysis, we can introduce IL-7, GATA3, TXN, ETS-1, CCR7, CD28, and CD5 as Crohn’s disease-related critical genes and possible biomarker panel." (PMID 33585004, 2020).
cyst (1 paper, 2019). A sac-like closed membranous structure that may be empty or contain fluid or amorphous material. "Surprisingly, only after achieving more than 50% inhibition of TxnR activity, was auranofin able to appreciably synergize with cyst(e)inase suggesting a considerable redundancy in the thioredoxin antioxidant system." (PMID 31231686, 2019).
delirium (1 paper, 2019). A disorder characterized by confusion; inattentiveness; disorientation; illusions; hallucinations; agitation; and in some instances autonomic nervous system overactivity. "Finally, AZGP1, MMP-9, neopterin, phenylalanine–tyrosine ratio, SERPINA3, thioredoxin, and 8-iso-prostaglandin F2α were linked to postoperative delirium." (PMID 31263968, 2019).
dermatophytosis (1 paper, 2019). A common fungal infection of the stratum corneum of the skin, hair, or nails by a dermatophyte. "The fungal thioredoxin was induced by superficial (keratin) and deep (elastin) skin elements suggesting that the product of this gene could be important in superficial and deep dermatophytosis." (PMID 31795354, 2019).
dilated cardiomyopathy (1 paper, 2023). Cardiomyopathy which is characterized by dilation and contractile dysfunction of the left and right ventricles. "The activity of the antioxidant thioredoxin system was also higher in dilated cardiomyopathy, but it has been postulated this might be an indirect reflection of excessive oxidative stress." (PMID 36997667, 2023).
endometrial cancer (1 paper, 2023). Primary or metastatic malignant neoplasm involving the endometrium (mucous membrane that lines the endometrial cavity). "CRNN, CALML3 and TXN predicted endometrial cancer with AUC values of 0.75 (0.64–0.84), 0.75 (0.65–0.84) and 0.75 (0.66–0.85) respectively." (PMID 36807337, 2023). "A four-marker panel comprising of SPRR1B, CRNN, CALML3 and TXN predicted endometrial cancer with an AUC of 0.80 (0.71–0.88)." (PMID 36807337, 2023). "Urine SPRR1B, S100A7, CALML3 and TXN were also found to have potential as endometrial cancer biomarkers." (PMID 36807337, 2023). "The four-marker panel comprising SPR1B, TXN, CRNN and CALM3 predicted endometrial cancer with an AUC of 0.78 (0.69–0.88)." (PMID 36807337, 2023).
endophthalmitis (1 paper, 2020). An infectious process affecting the internal structures of the eye. "Thus, the thioredoxin system may be speculated as an attractive antibiotic target for treatment of endophthalmitis induced by S. epidermidis." (PMID 32859978, 2020).
endotoxemia (1 paper, 2021). "In the early stage of endotoxemia, the thioredoxin system is one of the main forces regulating the oxidative stress balance." (PMID 33767697, 2021).
esophageal cancer (1 paper, 2022). A primary or metastatic malignant neoplasm involving the esophagus. "Additionally, mTOR and HDAC inhibitors converge on the TXNIP/thioredoxin pathway and cause oxidative stress and apoptosis in esophageal cancer." (PMID 36661507, 2022).
Ewing sarcoma (1 paper, 2022). A small round cell tumor that lacks morphologic, immunohistochemical, and electron microscopic evidence of neuroectodermal differentiation. "For example, in TNF-α treated Ewing's sarcoma cells, NF-κB activation increased both thioredoxin and MnSOD levels." (PMID 35841628, 2022).
Fanconi anemia (1 paper, 2017). Fanconi anemia (FA) is a hereditary DNA repair disorder characterized by progressive pancytopenia with bone marrow failure, variable congenital malformations and predisposition to develop hematological or solid tumors. "Our preliminary data indicate that TXN could upregulate the gene expression of the Fanconi anemia/BRCA DNA repair pathway (data not shown)." (PMID 29141658, 2017).
hepatoblastoma (1 paper, 2021). Hepatoblastoma (HB) is a malignant hepatic tumor and is the most common pediatric liver cancer. "The overexpression of NOS3 and concomitant NO mediate antiproliferative effects in hepatoblastoma cells through the modulation of the redox state of thioredoxin (Trx) and glutaredoxin (Grx)." (PMID 34200849, 2021).
ischemic heart disease (1 paper, 2018). "Intriguingly, a recent study by our group found that Notch1/Hes1 activation preserved thioredoxin activity and reduced MI/R injury in an acute hyperglycemic animal model, indicating that Notch1/Hes1 signaling might play a role in ischemic heart disease under diabetic condition." (PMID 29636838, 2018).
Liver abscess (1 paper, 2014). A circumscribed area of pus or necrotic debris in the liver. "The aim of present text is to define the importance of ONOO− as the main agent of liver abscess formation during amebic invasion and to explain the apparently superior capacity of the amoeba to defend itself against this toxic agent through the peroxiredoxin and thioredoxin system." (PMID 24822193, 2014). "The aim of the present text is to define the importance of ONOO− as the main agent of liver abscess formation during amebic invasion, and to explain the superior capacity of amoebas to defend themselves against this toxic agent through the peroxiredoxin and thioredoxin system." (PMID 24822193, 2014).
liver cirrhosis (1 paper, 2010). "Selenoamino acids are incorporated into selenoproteins (e.g. glutathione peroxidase and thioredoxin) that have strong associations with health status; deficiency in the liver has been linked to liver cirrhosis and hepatomegaly in rats, and impaired immune response in mice." (PMID 20929581, 2010).
lymph node metastasis (1 paper, 2017). "The expression level of TXN protein in NPC tissues with lymph node metastasis (P = 0.000) and distant metastasis (P = 0.026) were higher than those in NPCs without metastasis." (PMID 28107202, 2017). "Moreover, the expression level of TXN protein in NPC tissues with lymph node metastasis and distant metastasis was higher than that in NPC tissues without metastasis, which suggested that TXN may play an important role in promoting NPC metastasis." (PMID 28107202, 2017).
malignant brain tumors (1 paper, 2024). "Although similar profiles were observed, differences in relative abundances led to the identification of potential biomarkers, including caspase-3-like, protocadherin 4, deleted in malignant brain tumors, thioredoxin, papilin, annexin, cofilin and mucin-4 proteins." (PMID 39337441, 2024).
malignant pleural mesothelioma (1 paper, 2007). A malignant neoplasm that arises from mesothelial cells in the pleura and shows a diffuse growth pattern. "These genes have been found to be upregulated in malignant pleural mesothelioma and TXN is also known to be involved in the DNA-binding activity of NFKB." (PMID 17331233, 2007).
metastatic melanoma (1 paper, 2025). A melanoma that has spread from its primary site to another anatomic site. "TXN may suppress T-cell antitumor responses and favor metastatic melanoma by recruiting Treg cells." (PMID 39744566, 2025).
nasopharyngeal carcinoma (1 paper, 2017). A carcinoma arising from the nasopharyngeal epithelium. "In our previous study, five different secretory proteins, including GSN, ADAMTSL4, CALR, PPIA and TXN, have been identified to be associated with the nasopharyngeal carcinoma (NPC) metastasis." (PMID 28107202, 2017).
ovarian clear cell cancer (1 paper, 2023). An invasive malignant neoplasm that arises from the ovary and is characterized by a predominance of clear and hobnail malignant epithelial cells. "Compound 104 selectively inactivated thioredoxin and increased membrane peroxidation in human ES‐2 ovarian clear cell carcinoma cells similar to thioredoxin silencing." (PMID 36658724, 2023).
pancreatic adenocarcinoma (1 paper, 2024). "We explored the expression of several antioxidants (NRF2, GPX2, SOD1,2) and NRF2 target genes (NQO1, HMOX1, TXN) in 179 tumors and 171 normal tissues from the TCGA/GTEx pancreatic adenocarcinoma (PAAD) dataset." (PMID 38782891, 2024).
periodontal disease (1 paper, 2015). "Our current findings demonstrate an increase in antioxidant proteins–β-globin and Thioredoxin during the development of EG, suggesting an additional protective mechanism during this reversible phase of periodontal disease." (PMID 26779447, 2015).
primary immunodeficiency (1 paper, 2025). "Both TXN and DPP4 were found to be enriched in several shared pathways, including spliceosome, antigen processing and presentation, primary immunodeficiency, and regulation of autophagy." (PMID 40124361, 2025).
prostate tumor (1 paper, 2013). "In this regard, we recently demonstrated that a thioredoxin-targeted nanodevice selectively binds to reactive stroma in frozen prostate tumor tissue sections." (PMID 23762225, 2013).
rectal cancer (1 paper, 2018). A primary or metastatic malignant neoplasm that affects the rectum. "It is possible that the modulation of the peroxiredoxin/thioredoxin system could improve response to chemoradiotherapy for rectal cancer by acting on both radiotherapeutic and chemotherapeutic pathways." (PMID 30301137, 2018).
retinal ischemia (1 paper, 2022). A ischemic disease that involves the retina. "Using a PGE1 analog, the same group found that the treatment preserved TXN in retina up to 14 days in a retinal ischemia/reperfusion rat model, while TXN diminished in the non-treatment group." (PMID 36274523, 2022).
rheumatic diseases (1 paper, 2015). "We identified a total of eight differentially expressed genes (TNFSF10, CX3CR1, LY96, TLR5, TXN, TIA1, PRKCH, PRF1), each associated with at least 3 of the 4 studied rheumatic diseases." (PMID 26352601, 2015). "By jointly analyzing 6 published microarray gene expression datasets about RA, SLE, OA and AS, we identified eight genes (TNFSF10, CX3CR1, LY96, TLR5, TXN, TIA1, PRKCH, PRF1) presenting general importance to rheumatic diseases." (PMID 26352601, 2015).
thyroid cancer (1 paper, 2023). "Western blot assay demonstrated that the expression of TXN was highly increased in thyroid cancer samples compares to normal samples." (PMID 37684566, 2023). "We observed that TXN expression levels were significantly higher in thyroid cancer than in benign thyroid samples." (PMID 37684566, 2023). "SBP1 promoted tumorigenesis and dedifferentiation of thyroid cancer through positively regulating TXN." (PMID 37684566, 2023). "By searching the bioinformatics website GEPIA2, we observed that the level of TXN was increased in thyroid cancer patients than in normal control." (PMID 37684566, 2023). "In addition, TXN expression is positively correlated with the thyroid cancer stage." (PMID 37684566, 2023). "More interesting was the finding that knockdown of SBP1 inhibits tumor growth and progression of thyroid cancer, and promotes cell differentiation of BHT101 cells in a TXN/NIS dependent manner." (PMID 37684566, 2023). "Notably, TXN, a negative regulator of NIS, was found to be significantly upregulated in human thyroid cancer tissues, and it was positively regulated by SBP1." (PMID 37684566, 2023). "Mechanically, SBP1 interacts with and promotes TXN, which reduces NIS expression in thyroid cancer." (PMID 37684566, 2023).
ulcers (1 paper, 2012). "Macroscopic (edema, hemorrhage, and ulcers) and histological (necrosis, submucosal edema, neutrophil infiltration) findings induced by indomethacin were significantly reduced by pretreatment with food pellets containing thioredoxin." (PMID 22402774, 2012).
Wilson disease (1 paper, 2021). A very rare inherited multisystemic disease presenting non-specific neurological, hepatic, psychiatric or osseo-muscular manifestations due to excessive copper deposition in the body. "The TXN system genes have increased DNA methylation levels in the liver of Wilson’s disease patients and in the disease mouse model where copper induced oxidative stress is a major factor." (PMID 34208977, 2021).
cancer (227 papers, 2005 to 2026). A tumor composed of atypical neoplastic, often pleomorphic cells that invade other tissues. "In pathological states such as cancer, cardiovascular diseases, and neurodegenerative diseases, abnormal regulation of the thioredoxin system is closely associated with the onset and progression of diseases." (PMID 38685115, 2024). "In conclusion, we identified PIK3R1, CCND1, TERF2IP, SLC25A4, CAPN2, and TXN as potential markers associated with both cancer and MN." (PMID 38846934, 2024). "At the same time, thioredoxin has shown cancer risk in both animal studies and human clinical trials." (PMID 38001457, 2023). "The enhanced TXN expression in tumors has been linked to a worse survival rate of patients in several carcinomas." (PMID 37037466, 2023). "The antioxidant thioredoxin system has also been reported to be upregulated in cancer cells and linked to cancer development, relapse, and chemoresistance in acute leukemia." (PMID 35887320, 2022). "The thioredoxin antioxidant pathway is upregulated in tumors and simultaneous inhibition of the thioredoxin and glutathione antioxidant pathways causes synergistic cancer cell death." (PMID 32029902, 2020). "Similar to PRDXs, a large number of studies have shown that thioredoxin and TrxR1 are overexpressed in various cancers and are associated with resistance to anticancer drugs." (PMID 32605023, 2020). "Overexpression of thioredoxin has been implicated in the pathogenesis of advanced malignancies, including solid cancer and hematological malignancy." (PMID 29482577, 2018). "Inhibition of the thioredoxin (Trx) system can disrupt the homeostasis of cancer cells causing a dramatic imbalance between the formation and the removal of ROS." (PMID 27588488, 2016). "Imbalances in the NADPH/thioredoxin reductase/thioredoxin system are associated with a number of pathologies, particularly cancer, and a number of clinical trials for thioredoxin and thioredoxin reductase inhibitors have been carried out or are underway." (PMID 27716777, 2016). "Increased glutathione (GSH) and thioredoxin (Trx) metabolism are mechanisms that are widely implicated in resistance of cancer cells to chemotherapy." (PMID 23118946, 2012). "Thioredoxin protein levels are elevated in many human primary cancers and this high expression is associated with aggressive tumor growth and inhibited apoptosis, as well as decreased patient survival and resistance to anti-cancer treatments." (PMID 24281068, 2010). "The flavoprotein thioredoxin has been shown to be upregulated in several human tumors and is implicated in both cancer cell growth and apoptotic resistance." (PMID 19061505, 2008). "Auranofin’s anti-cancer activity has been linked to the accumulation of ROS via the inhibition of the redox enzymes, GPx and TrxR, which play important roles in the glutathione and thioredoxin redox systems, respectively." (PMID 41363856, 2026). "The impaired TXNIP/TXN redox homeostasis might be associated with development of multiplex cancer especially of EVT in ESRD/ACRD kidney." (PMID 39020292, 2024). "Molecular dynamic (MD) simulations conducted for both conjugates con7 and con3 revealed that the conformation of these analogues exposed the disulfide bond to the surrounding solvent environment, rendering it susceptible to the thioredoxin system within cancer cells." (PMID 37894912, 2023). "The association of TXN with cancers was analyzed by immunohistochemistry using anti-TXN antibody." (PMID 28107202, 2017). "Studies of polymorphisms in the TXN gene, encoding thioredoxin, are few in cancer." (PMID 25416100, 2014). "Therefore, our results indicated that the downregulation of RBM24 in female LIHC patients could cause the loss of normal function of TXN and inhibit cancer progression." (PMID 39175079, 2024).